SALRNA2 (senescence associated long non-coding RNA 2)
Synonyms: SAL-RNA2; XLOC_025931
Gene: Long non-coding RNA gene on chromosome 15 (70,635,249 to 70,637,314, forward strand). Ensembl gene ENSG00000280515.
Diseases named in the same sentence as SALRNA2 in open-access papers:
SALRNA2 is named in the same sentence as 1 disease in open-access papers, as found by Europe PMC text mining. Sharing a sentence is not in itself a finding about the gene and the disease.
SALRNA2 shares sentences with these, for which no sentence is quoted: synovial sarcoma (1 paper).